CCR2 (C-C motif chemokine receptor 2)
Diseases named in the same sentence as CCR2 in open-access papers (continued):
Sharing a sentence is not in itself a finding about the gene and the disease.
tumor (continued). "Serum CCL2 and CCL2/CCR2 expression level were remarkably increased in NPC patients compared to non-tumor patients by ELISA and IHC analyses." (PMID 26701209, 2016). "While CCR2+ myeloid cells contribute to tumor cell metastasis, CCR2+ endothelium is activated by CRC-derived CCL2, which increases vascular permeability and cancer cell extravasation through the JAK2-Stat5 and p38MAPK pathways." (PMID 27136535, 2016). "CCR2 high expression was correlated with tumor invasion depth (P=0.006 and P=0.004, respectively), lymph node metastasis (P=0.038 and P=0.011, respectively) and TNM stage (P=0.003 and P=0.001, respectively) in the two independent sets." (PMID 26992207, 2016). "Paradoxically, we observed that targeted disruption of Ccr2, which encodes the only high affinity signaling receptor for CCL2, promotes HER2/neu-driven tumor growth and shortens overall survival." (PMID 27820834, 2016). "Using CCR2 antagonists inhibited tumor growth and prevents metastasis, as well as reducing inflammation and joint destruction in a murine model of adjuvant-induced arthritis." (PMID 26997761, 2016). "Consistently, we detected the expressions of CCR2 and TNFα on hepatic F4/80+ macrophages were markedly lower than that from tumour." (PMID 27270308, 2016). "Although the highly aggressive behavior of tumors in Ccr2-/- mice appears to be a consequence of more than just loss of CCR2 signaling, the tumors in these mice provided a clue about a mechanism by which intact CCL2/CCR2 signaling influences tumor progression." (PMID 27820834, 2016). "In a genetic mouse model of CRC, inactivation of Ccl2 caused depletion of CCR2+ TAM at the tumor site and reciprocal accumulation of CTL, which prevented tumor progression." (PMID 27136535, 2016). "This suggests that the CCL2/CCR2 axis promotes tumor growth in the MMTV-neu model and genetic disruption of Ccr2 promotes tumor growth through other pathways." (PMID 27820834, 2016). "In addition, CCL2/CCR2 signaling could educate tumor-associated macrophages (TAMs) to enhance the production of several kinds of immunosuppressive cytokines and chemokines, which in turn facilitate the progression of tumors and exert an unfavorable effect on cancer patients." (PMID 27409666, 2016). "Blockade of CCL2/CCR2 axis in various tumors displayed remarkable therapeutic effects as the versatile functions of macrophages in tumor progression." (PMID 27888616, 2016). "It is likely that targeting both processes via CCR2/CCR5 inhibition blocks myeloid entry into the tumor resulting in improved RT efficacy of radio-responsive tumors." (PMID 27852031, 2016). "It has been reported that CCL2 and its primary receptor CCR2 have the ability to recruit monocyte from peripheral blood to tumor site regulate the mobilization of macrophages." (PMID 27409666, 2016). "Apart from recruiting and educating TAMs, CCL2/CCR2 has been reported to be responsible for the accumulation of myeloid-derived suppressor cells (MDSCs) in tumor sites." (PMID 27409666, 2016). "CCL2 acting via its receptor C-C chemokine receptor 2 (CCR2) is a direct mediator of monocyte recruitment to the primary tumor and to metastases in the Polyoma Middle T oncoprotein (PyMT) model." (PMID 27191744, 2016). "CCL2 and its receptor CCR2 are the chemokines largely participating in tumor microenvironment by regulating macrophage mobilization and infiltration, and also by recruiting inflammatory monocytes from bone marrow to peripheral sites of inflammation." (PMID 26701209, 2016). "Schmall et. al. demonstrated that treating mice with a CCR2 antagonist led to reduced tumor growth and fewer metastases in the lung." (PMID 27852031, 2016). "The impact of ranitidine on monocyte responses and the role of CCR2 in ranitidine-induced tumor growth inhibition were also investigated." (PMID 26863636, 2016). "Tumor tissues showed more CCR2 staining compared to peritumoral normal tissues which was obtained from tumor resection margin." (PMID 26992207, 2016).
tumor (continued). "It was noteworthy that the inflammatory environment induced by a GBM tumor in the CNS, like dermis inflammation in the ear15, favored the differentiation of CCR2+ monocytes into a CCR2+ DC P2 or P3 phenotype." (PMID 27193333, 2016). "Again, the PDL1 expressing population of tumor infiltrating DC expressed proteins indicating monocyte origin (i.e., CCR2+, FcγRI+) and co-expressed iregDC markers CD39 and CD95." (PMID 26808628, 2016). "The CCL2/CCR2 chemokine axis plays a pivotal role in the migration of MDSCs in cancer, and impairment of CCL2/CCR2 signaling inhibits tumor growth." (PMID 26901500, 2016). "In contrast, disruption of Ccr2, which encodes CCL2’s sole signaling receptor, accelerated tumor development, shortened host survival, and mobilized EPCs." (PMID 27820834, 2016). "In an orthotopic transplantation mouse model of pancreatic cancer, CCR2 inhibitors depleted inflammatory monocytes and macrophages, which resulted in decreased tumor growth and reduced metastasis." (PMID 27136535, 2016). "Together, our data showed the infiltrated mast cells in the tumor microenvironment enhance BCa metastasis via stimulating ERβ/CCL2/CCR2 EMT/MMP9 signals both in vitro and in vivo." (PMID 26556868, 2016). "Being a critical chemokine receptor in chemoattracting myeloid cells into tumor tissues, C-C chemokine receptor 2 (CCR2) has been detected in many malignant tumors." (PMID 26992207, 2016). "To find evidence for such changes, we analyzed gene expression profiles of circulating monocytes isolated from tumor-free wild type, Ccl2-/-, and Ccr2-/- mice." (PMID 27820834, 2016). "In a recent study, anthracyclin chemotherapy induced Ly6Chi CD11c+ cells at the tumor site by an ATP- and CCR2/CCL2-dependent mechanism." (PMID 26635798, 2015). "HBD3 chemoattract monocytes to the tumor microenvironment via chemokine receptor 2 (CCR2), further supporting the role of human β defensins in establishing the tumor microenvironment, which leads to tumor progression." (PMID 25657649, 2015). "CCL2 (MCP1) is a cognate ligand for chemokine receptor CCR2, which is expressed by monocytes in peripheral blood and plays multiple roles in cancer, including chemoattraction of circulating CCR2-positive monocytes/macrophages to the tumor vicinity." (PMID 25978454, 2015). "For example, it has been reported that expression of chemokine receptors CXCR2 and CCR2 by CAR modified T cells can facilitate their localization to the tumor site and hence antitumor immune responses." (PMID 25460506, 2015). "Overall, a high CCL2 expression level is correlated with a worse outcome in many cancer types, suggesting that CCR2+ inflammatory monocytes often function as tumor-promoting cells." (PMID 24723924, 2014). "CCR2 is expressed on both Vγ1+ and Vγ4+ γδ T cells, and is necessary for the accumulation of γδ TILs to the tumor bed." (PMID 25405356, 2014). "Deletion of CCR2(+) MDSCs using a toxin-mediated ablation strategy increased recruitment of activated CD8(+) T cells into the tumor and thus restored antitumor defense." (PMID 25110692, 2014). "Subsequently, splenic Ly6Chigh monocytes are recruited to the tumor in a CCL2/CCR2-dependent fashion, where they contribute significantly to the TAM pool and tumor progression." (PMID 24723924, 2014). "BAL macrophage content and tumor numbers from urethane-exposed CCR2−/− and wild-type mice were similar between genotypes at each time point." (PMID 25505466, 2014). "For instance, systemic administration of CCL2-neutralizing antibodies in tumor-bearing mice or the short-hairpin RNA knockdown of CCR2 in the cancer cell lines significantly reduced tumor growth along with reduced TAM recruitment." (PMID 25125485, 2014). "A slight, but significant increase in tumor size in the CCR2−/− mice compared to wild-type littermates was detected at the 44-week time point, which is consistent with the poorer survival observed in human NSCLC patients with low-CCL2 expression." (PMID 25505466, 2014).
tumor (continued). "This PTM reduces the binding affinity of CCL2 to its receptor CCR2, affecting drastically tumor homing of CD8+ T lymphocytes." (PMID 24605112, 2014). "Genetic ablation of CCR2 markedly attenuates tumor formation with reduced HSC accumulation and MMP-2 expression." (PMID 24966464, 2014). "A similar shift to neutrophil-rich leukocyte infiltration was previously found when different tumor cell lines were injected into CCR2−/− mice." (PMID 23527025, 2013). "Following their entry into the tumor the monocytes develop a selective defect in CCR2 expression, which prevents the chemokine scavenging function of the monocytes while keeping them arrested within the tumor." (PMID 24384839, 2013). "Neutralizing antibodies to CCL2 that blocked CCR2 reduced myeloid suppressor cell migration to the tumor site and reduced MSC-promoted tumor growth." (PMID 23533456, 2013). "After macrophages have successfully migrated into the hypoxic region of the tumor, their movements become restricted by decreased expression of CCR2 and CCR5 via hypoxia-mediated down-regulation of these receptors." (PMID 23847541, 2013). "Collectively, these results suggest that BM CD11b+CCR2+ cells home via CCR2 to the tumor to support its angiogenesis and subsequent growth by eliciting the production of angiogenic factors and possibly by other mechanisms, yet to be identified." (PMID 22279523, 2012). "The first experiment compared the ability of either BM CD11b+ cells from CCR2+ donors to support tumor development in CCR2−/− mice, and the other experiment compared the ability of purified CX3CR1 (GFP+) cells from CCR2+ mice to do so." (PMID 22279523, 2012). "Using this system we dissected the selective contribution of CX3CR1+CCR2+ cells, which comprise only about 7% of CD11b+ BM cells, to tumor development and angiogenesis." (PMID 22279523, 2012). "Then GFP+ cells were isolated using FACSAria Cell-Sorting System (96% purity), and administered (3×106/mouse) to CCR2−/− mice bearing a CCR2+ tumor, under the same experimental conditions." (PMID 22279523, 2012). "It is likely that most of contribution of the BM transferred cells from CCR2+ to CCR2−/− mice resulted from the ability of CCR2+ monocytic cells to directly support the tumor, and to recruit other BM cells." (PMID 22279523, 2012). "It is intriguing, however, that even BM CCR2+ cells (macrophages and DC) are only a small portion of BM cells that home and produce cytokines, chemokines, and angiogenic factors at the tumor site, and yet their role in such tumors is so essential." (PMID 22279523, 2012). "Collectively, these results suggest that reduced luciferase activity in tumors from CCR2−/− mice resulted from impaired tumor proliferation followed by increased necrosis at the central areas of the tumor." (PMID 22279523, 2012). "We then monitored micro-metastases formation at the brain, liver, bones and lungs of CCR2−/− and WT mice subjected to i.v. + s.c administration of tumor cells." (PMID 22279523, 2012). "The basic experimental system is identical to the one we used above in which only the tumor cells expressed CCR2." (PMID 22279523, 2012). "Auto fluorescence staining of necrotic areas indicated large necrotic areas at the primary tumor site developed in CCR2−/− mice, when compared to wild-type counterparts (b compared to a)." (PMID 22279523, 2012). "The next approach was to use our experimental system to delineate the direct contribution of the interaction between the CCR2+ tumor cells and the CCL2 ligand on tumor growth." (PMID 22279523, 2012). "Our results showing that BM reconstitution of CCR2+ cells in CCR2−/− mice bearing a CCR2+ tumor fully reconstitutes its development; therefore support the pivotal role of these receptors on BM cells in supporting tumor angiogenesis." (PMID 22279523, 2012). "Compared with wild-type mice, CCR2−/− mice exhibited depressed uptake of intravenously administered OVA protein even when they were administered with the parental tumor." (PMID 22815949, 2012).
tumor (continued). "We show that the administration of CCR2-Ig that selectively neutralize CCL2 entirely suppress tumor development in CCR2−/− mice, where the only cells that were CCR2+ were the tumor cells." (PMID 22279523, 2012). "In an attempt to delineate the role of BM CCR2+ DC/monocytic cells to tumor development we have conducted two complementary sets of adoptive transfer experiments." (PMID 22279523, 2012). "Intriguingly, CCR2-expressing monocytes have been recently shown to have an immune regulatory role via suppression of T cell activities under tumor and autoimmune conditions." (PMID 21991368, 2011). "For example, it was believed that neutralizing CCL2 would be of beneficial potential for the control of CCR2-expressing tumor cells." (PMID 21943176, 2011). "Ten tumor reactive T-cell lines derived from TIL of additional CRC patients were analyzed for CCR2 expression and four of these showed CCR2 expression." (PMID 21450101, 2011). "Expression of CCR2 in four additional CRC patients' lymphocytes isolated from infiltrating tumor tissues suggests their role in migration in other CRC patients." (PMID 21450101, 2011). "Our results indicate that the PDAC patients with the best clinical outcome retained high expression of ICOSL on both MDCs and PDCs and CCR2 on PDCs, which indicate that the DCs were less affected by the tumor." (PMID 20976171, 2010). "Double-staining of the specimen with antibodies to F4/80 and mouse CCR2 indicated infiltration of CCR2+ mouse macrophages in the tumor established by hBD-3 overexpressing cells (CCR2+ mouse macrophages are indicated with white arrows)." (PMID 20544025, 2010). "We previously reported that CCL2 is generally expressed in various tumor types of both human and mouse and CCR2 is expressed by MDSCs." (PMID 20111717, 2010). "CCR2, a critical member of the chemokine receptor family, is primarily expressed on the surface of monocytes, macrophages, and some T cells and plays a pivotal role in shaping and regulating the tumor immune microenvironment." (PMID 41497137, 2026). "CCR2-independent subset of macrophages (predominantly M2c subtype) in CA becomes the dominant resident macrophage population and becomes even more abundant following transformation into tumor." (PMID 41438574, 2026). "The CCR2-DC-ANVs target tumour by leveraging the C-C motif chemokine ligand 2 (CCL2) in tumours." (PMID 42209521, 2026). "We used Ccr1- and Ccr2-deficient mice and two different tumor cells lines, MC38 and LLC1 with and without Ccl2-deficiency in vitro and in vivo." (PMID 39566333, 2025). "In mice, inducible non-classical monocytes can migrate into both vascular and extravascular tumor microenvironments via the CCR2/CCL2 axis, where they release CCL6 to recruit NK cells that promote tumor lysis independent of T and B lymphocytes, attenuating metastasis." (PMID 40427136, 2025). "Tumor growth also promotes the differentiation of CCR2+ monocytes into TAMs." (PMID 41058699, 2025). "CCR2 inhibitors (e.g., PF‐0413630950 and CCX87251), have demonstrated efficacy in reducing tumour‐associated macrophage infiltration in cancer models and may offer similar benefits in limiting lung inflammation in this context." (PMID 39902678, 2025). "Together, these results showed that adipocyte-secreted CCL2 contributed to cisplatin resistance through both paracrine signaling to tumor cells and autocrine stimulation of lipolysis in adipocytes, with both pathways being effectively targeted by CCR2 blockade." (PMID 41276817, 2025). "Moreover, tumor uptake in wild-type mice was markedly higher than in MMR-deficient and CCR2-deficient mice, confirming its specificity for MMR and macrophages." (PMID 40725764, 2025). "Additionally, studies have shown that a tumor adaptation mechanism exists whereby the Ccl2/Ccr2/Cxcl2 axis promotes the recruitment of monocytes which in turn can acquire pro-tumorigenic phenotypes and contribute to immunosuppression." (PMID 40568084, 2025).